APOE (apolipoprotein E)
Diseases named in the same sentence as APOE in open-access papers (continued):
Sharing a sentence is not in itself a finding about the gene and the disease.
atherosclerosis (continued). "It was revealed that only after 3 weeks of age in SR-BI/apoE double knockout mice atherosclerosis in the coronary arteries and aortic sinus, enlargement of the heart, and fibrosis of the heart start developing." (PMID 36118710, 2022). "Taken together, both the in vitro and in vivo data revealed the ability of apoE to suppress lymphocyte response to inflammation, thereby illustrating another mechanism by which apoE protects against atherosclerosis in an isoform-dependent manner." (PMID 36077289, 2022). "Because it is believed that the injury of endothelial cell mediate the atherosclerosis progression, we further determined the anti-atherosclerotic activity of dihydrohomoplantagin or homoplantaginin in apoE-/- mice." (PMID 35335352, 2022). "In conclusion, T2D-accelerated atherosclerosis correlates with a reduction in miR-21 and miR-33a and an elevation in miR-122 and miR-3064-5p in circulation and the liver of ApoE-/- mice." (PMID 36286043, 2022). "The atherosclerosis model of ApoE−/− mice was used to confirm the targeting and accumulation specificity in atherosclerotic plaques." (PMID 35118420, 2022). "In conclusion, after 16 weeks of continuous high-fat diet combined with binding stimulation, ApoE−/− mice showed symptoms of atherosclerosis co-depression." (PMID 35558553, 2022). "The distribution of atherosclerotic lesions in the aorta and its branches of ApoE knockout (ApoE−/−) mice is like that of patients with atherosclerosis." (PMID 34797426, 2022). "In an atherosclerosis model established in ApoE−/− mice, PMSN encapsulating anti-CD47 antibody delivery significantly promoted the efferocytosis of necrotic cells in plaques." (PMID 35118420, 2022). "In summary, we showed that increasing the NAD+ level or its biosynthesis attenuates vascular inflammation, oxidative stress, endothelial dysfunction, and atherosclerosis in endothelial cells and in hyperlipidemic ApoE−/− mice." (PMID 35453391, 2022). "Two gene-targeted murine models of atherosclerosis, the apolipoprotein E knockout and the LDL-receptor knockout mice, possess substantiated to live workable for this research." (PMID 35269559, 2022). "ApoE−/− p47 phox−/− or gp91 phox−/− mice have significantly decreased atherosclerosis, O2•− and increased NO in the aortas vs. ApoE−/− mice." (PMID 35883899, 2022). "Overexpression of IKKβ in the liver can aggravate atherosclerosis development in APOE*3-Leiden mice." (PMID 33459922, 2022). "ApoE-knockout mice were more likely to develop atherosclerosis due to the accumulation of unprocessed lipids, difficulty in endocytosis of IDL triglycerides, and lower production of HDL." (PMID 35269673, 2022). "ApoE−/− mice haploinsufficient for the DNA repair protein kinase ATM (ataxia telangiectasia mutated) show increased nuclear DNA damage and accelerated atherosclerosis." (PMID 36497101, 2022). "In vivo-administration of αIL17A Affibody molecule in atherosclerosis-prone ApoE−/− mice attenuated plasma levels of inflammatory markers and downregulated Th17 associated genes in splenocytes." (PMID 35282365, 2022). "CMA activity is lower in atherosclerosis plaques of patients, and CMA controls inflammasome activation to reduce atherosclerosis in ApoE–/– mice." (PMID 37425656, 2022). "In in vivo experiments, GPIbα + monocytes adhered to TGF-β1-stimulated vascular smooth muscle, whereas in the apolipoprotein E (APOE) − /– atherosclerosis model, GPIbα + monocytes adhered to carotid arteries." (PMID 36441349, 2022). "Paeonol, a phenolic compound found in Paeonia suffruticosa, retarded atherosclerosis progression in apoE−/− mice by upregulation of ABCA1-mediated enhancement of cholesterol efflux and downregulation of CD36." (PMID 36297390, 2022). "Artemisinin has also been reported to attenuate atherosclerosis in HFD-fed ApoE-KO mice by enhancing autophagic activity of macrophages." (PMID 35237600, 2022).
atherosclerosis (continued). "In this study, we studied the role of PAD4 for the development of atherosclerosis and disease progression using irradiated ApoE–/– mice reconstituted with ApoE–/–/Pad4–/– bone marrow cells and challenged with a high-fat diet." (PMID 36465436, 2022). "Decreasing the acylcarnitine pools in apolipoprotein E knockout (apoE−/−) mice is able to attenuate the development of atherosclerosis." (PMID 36230983, 2022). "Our results are consistent with previous studies, out of the IH context, which demonstrated that the inhibition of VE-cadherin cleavage, tyrosine-kinases, src-kinases and HIF-1 protects against atherosclerosis in ApoE-/- mice." (PMID 35806017, 2022). "In an inflamed atherosclerosis model using casein injection in ApoE KO mice, HFD induced hyperlipidemia-mediated cardiac fibrosis." (PMID 35130955, 2022). "For example, in atherosclerosis-prone apolipoprotein E (ApoE)-null mice, DNA methylation changes occurred in both peripheral blood leukocytes and the aorta prior to the formation of vascular lesions." (PMID 35586748, 2022). "Specifically, ApoE KO mice served as the animal model for hyperlipidemia and atherosclerosis and were continuously fed with a Western diet (WD) for the rapid development of these diseases." (PMID 36408520, 2022). "The activation of AHR induces macrophage activation and foam cell formation in apolipoprotein E (ApoE) knockout mice, participates in vascular inflammation, and eventually develops atherosclerosis." (PMID 36615808, 2022). "Collectively, dihydrohomoplantagin and homoplantaginin protected VECs by activating Nrf2 and thus inhibited atherosclerosis in apoE-/- mice." (PMID 35335352, 2022). "In apolipoprotein E–/– mice, FGF-21 deficiency results in accelerated atherosclerosis and premature death, along with hypoadiponectinemia and hypercholesterolemia." (PMID 35186330, 2022). "MALAT1−/+ ApoE−/− mice suffered accelerated atherosclerosis despite normal diet compared to ApoE−/− mice." (PMID 36552736, 2022). "ApoE terminal glycosylation is suggested to protect against spontaneous self-aggregation in atherosclerosis." (PMID 35625910, 2022). "Polydatin synergizes with P. sibiricum polysaccharides in preventing the development of atherosclerosis in ApoE–/– mice by inhibiting the TLR4/MyD88/NF-κB signaling pathway." (PMID 35845572, 2022). "In an IL-35 treatment model, IL-35 increased splenic Tregs and inhibited atherosclerosis in ApoE−/− mice." (PMID 36211578, 2022). "It was also observed that the suppression of Drp1 can decrease endothelial dysfunction and atherosclerosis in apolipoprotein E (ApoE) knockout diabetic mice and, moreover, reduce the calcification of smooth muscle cells caused by oxidative stress." (PMID 35328371, 2022). "It as been proposed that SLG2 inhibition reduces atherosclerosis in ApoE−/− mice through regulation of the NLRP3 inflammasome expression in macrophages." (PMID 35348183, 2022). "It has been reported as the most abundant protein in HDL isolated from atherosclerotic lesions, indicating an important role of apoE in atherosclerosis pathophysiology." (PMID 35371605, 2022). "Taken together, our findings suggested that the adoptive transfer of MDSCs into ApoE−/−Fas−/− mice aggravated atherosclerosis and SLE, whereas depleting MDSCs using anti-Gr-1 antibody ameliorated SLE and atherosclerosis in ApoE−/−Fas−/− mice." (PMID 35850768, 2022).
atherosclerosis (continued). "Using an apolipoprotein/ATM heterozygous (Atm+/- /ApoE-/- ) mice, Mercer and co-workers revealed that Atm+/- /ApoE-/- mice displayed accelerated atherosclerosis and multiple phenotypes of metabolic syndrome." (PMID 36354755, 2022). "C1q–apolipoprotein-E (ApoE) complexes have emerged as markers for ongoing complement activity in atherosclerosis in vivo." (PMID 35562585, 2022). "It has been reported that Tan IIA downregulates mmu-miR-375 to increase the KLF4 protein expression and ameliorate atherosclerosis in ApoE knockout mice." (PMID 35832651, 2022). "Oppositely, it has also been reported that inulin can regulate gut microbiota, but cannot improve atherosclerosis in hypercholesterolemic ApoE*3-Leiden." (PMID 36219347, 2022). "Quercetin prevents the development of atherosclerosis in ApoE−/− mice by regulating the expression of PCSK9, CD36, PPARγ, LXRα, and ABCA1." (PMID 35845584, 2022). "Our recent studies showed that CD4+LAP+ and CD4+CD25+ Tregs are suppressed in ACS and that CD4+LAP+ and CD4+CD25+Foxp3+ T cells induced by nasal-oxidized low-density lipoprotein suppress effector T cell responses and attenuate atherosclerosis in ApoE−/− mice." (PMID 36405994, 2022). "Based on 1H-NMR metabonomics, this study investigated the serum metabolic changes in ApoE−/−;SAP−/− mice compared with ApoE−/− mice during the whole progression of atherosclerosis." (PMID 36557316, 2022). "In vivo, a high-fat-diet-induced atherosclerosis model was established in apolipoprotein E knockout mice." (PMID 35968506, 2022). "ApoE knockout mice are widely used as an atherosensitive platform to evaluate the effect of modulator genes on the development and progression of atherosclerosis." (PMID 35256637, 2022). "In Apolipoprotein E (ApoE) null mice, e-cigarettes induced a cardiac inflammatory phenotype associated with increased serum levels of FFA and atherosclerosis." (PMID 35463745, 2022). "AngII infusion led to vascular expansion and development of atherosclerosis in aortic arches, vascular expansion and development of AA in suprarenal aortas in Col1a2+/G610C.ApoE-/- mice." (PMID 35966595, 2022). "Our previous study indicates that loss of BMP4 in PVAT impaired PVAT metabolism and accelerated the development of atherosclerosis in ApoE–/– mice." (PMID 36457800, 2022). "To investigate the influence of a WD (high-fat diet) and STZ-induced diabetes on atherosclerosis in ApoE KO male mice, we performed en face staining of the aorta with Sudan IV." (PMID 36408520, 2022). "And deficiency of CD11c on APOE double deficiency mice reduces the firm attachment of monocytes to VCAM1, P Selectin which are proinflamatory cytokine for the development of atherosclerosis." (PMID 35241081, 2022). "We investigated the effect of bromelain on atherosclerosis and its regulatory mechanisms in hyperlipidemia and atheroprone apolipoprotein E-null (apoe−/−) mice." (PMID 36670934, 2022). "Dehydrocorydaline alkaloid has been shown to ameliorate atherosclerosis in ApoE-/-mice via inflammatory inhibition targeting through macrophage p65- and ERK1/2-mediated pathways." (PMID 35888597, 2022). "Coherently, ox‐LDL‐PM‐EVs carrying miR‐19b‐3p can accelerate the progression of atherosclerosis in ApoE−/− mice." (PMID 34910364, 2022). "Our findings revealed that SIRT6 in macrophages inhibited HFD-induced atherosclerosis in ApoE-/- mice by reducing the levels of H3K9ac and H3K56ac." (PMID 35855341, 2022).
atherosclerosis (continued). "The importance of apoE-mediated plasma lipoprotein clearance and atherosclerosis was established by the robust hyperlipidemia and atherosclerosis observed in ApoE−/− mice." (PMID 36077289, 2022). "Although validation of our observations should be obtained in genetically modified mice (with LDL receptor or apolipoprotein E knockout, known to develop atherosclerosis), our findings clearly highlighted hyperlipidemia repression by PACs." (PMID 36670951, 2022). "To investigate the functional significance of Atox1 in atherosclerosis in vivo, we used either Atox1−/− mice crossed with ApoE−/− mice (Atox1−/−/ApoE−/−) or ApoE−/− (control) mice on a 4-month Western diet." (PMID 36139494, 2022). "Besides, obesity may be an important factor in atherosclerosis and the apolipoprotein E-deficient (Apoe knockout) mice with poor lipoprotein clearance, would be stable animal model with accumulation of cholesterol ester-enriched particles in the blood for atherosclerotic pathogenesis." (PMID 35256637, 2022). "In ApoE−/− mice, 1.3% ʟ-carnitine-induced atherosclerosis, that was ameliorated by allicin supplementation, indicating the potential anti-atherosclerotic activity of allicin." (PMID 35087050, 2022). "Oral Rg3 restrained the formation of atherosclerosis and inflammation in ApoE−/− mice via the regulation of peroxisome proliferator-activated receptor γ (PPARγ)/focal adhesion kinase (FAK)." (PMID 36133804, 2022). "GSIs have been shown to reduce atherosclerosis progression in ApoE−/− mice, which exert reduced ICAM-1 expression and total plaque areas." (PMID 35459215, 2022). "A similar effect is observed in ApoE−/− mice with atherosclerosis, where canagliflozin reduces the number of infiltrated macrophages in the atheroma plaque, which is related to the halting of the progression of the disease." (PMID 35628443, 2022). "Our previous research showed that C. pneumoniae infection induced aberrant VSMC migration, thereby promoting atherosclerosis in ApoE‐/‐ mice." (PMID 35493076, 2022). "Hyperlipidaemic APOE*3Leiden.CETP transgenic mice not only develop spontaneous atherosclerosis but can also be used for induction of lesions in the aortic valve with similarities to changes observed in human CAVS." (PMID 35751904, 2022). "In conclusion, we proposed a biomathematical model of atherosclerosis development in APOE -/- mice including a well-defined set of physiological parameters." (PMID 35921269, 2022). "Transplantation of PVAT from high-cholesterol diet-fed apolipoprotein E (ApoE) knockout mice to normal chow-fed ApoE-knockout mice resulted in a striking increase in atherosclerosis development." (PMID 35885059, 2022). "This strain was found to elevate serum TMAO and promote the formation of atherosclerosis in ApoE−/− mice when co-administered with choline." (PMID 35273169, 2022). "We then determined the protective effect of bufalin on atherosclerosis by using ApoE-/- prevention model." (PMID 36263184, 2022). "The therapeutic effects of a naive exosome or a modified exosome on atherosclerosis were examined in ApoE(−/−) mice fed a high-fat diet." (PMID 35055187, 2022). "Collectively, these results suggested that the downregulation of miR-33a promoted hepatic cholesterol efflux contributing to aggravated atherosclerosis in ApoE-/- mice with T2D." (PMID 36286043, 2022). "We also detected the level of CRP (C-reactive protein) in ApoE−/−+PBS and ApoE−/−+EPA group to show the effects of EPA in atherosclerosis." (PMID 35464772, 2022). "We aimed to elucidate the effect of neonatal subcutaneous BCG vaccination—analogous to human BCG vaccination—on atherosclerosis development in ApoE−/− mice." (PMID 36290415, 2022).
atherosclerosis (continued). "of Lactobacillaceae, Lactobacillus acidophilus ATCC 4356, prevented the progression of atherosclerosis in ApoE-/- mice by inhibiting intestinal cholesterol absorption." (PMID 36451858, 2022). "We previously demonstrated that immune modulation of T cells reactive with the ApoB-100 peptide P210 in ApoE–/– mice reduces atherosclerosis." (PMID 35536648, 2022). "Here, we investigated the effects of low-dose GA administration on diet-induced metabolic disorders and atherosclerosis in the atherosclerosis-prone apolipoprotein E (Apoe) knockout mice fed on a high-fat Western-type diet (WTD) for 8 weeks." (PMID 35652108, 2022). "In this study, we used the well-characterized HO-1 inducer hemin and inhibitor SnPP to examine the protective role of HO-1 in the ApoE−/− atherosclerosis mouse model." (PMID 35281895, 2022). "Collectively, dihydrohomoplantagin and homoplantaginin protected VECs by activating Nrf2 and thus restricted atherosclerosis in apoE-/- mice." (PMID 35335352, 2022). "The ApoE–/– mouse is a well-established animal model that has been applied extensively to research on the mechanism of atherosclerosis development." (PMID 35563294, 2022). "Taken together, these findings suggested that ApoE−/−Fas−/− mice showed typical lupus-like symptoms and atherosclerosis accompanied with increasing MDSCs." (PMID 35850768, 2022). "Fucoidan, a marine sulfated polysaccharide derived from brown seaweeds with anti-inflammatory activity, has also been reported to alleviate atherosclerosis in HFD-fed ApoE-KO mice by enhancing autophagic activity." (PMID 35237600, 2022). "We focused on the effects and mechanisms of the ARCR herb pair attenuation of atherosclerosis in apolipoprotein E knockout (ApoE-/-) mice." (PMID 35178108, 2022). "Here, this study provides the first evidence that β-sitosterol inhibited TMA production in ApoE–/– mice by reshaping the gut microbial structure and attenuated atherosclerosis." (PMID 36386330, 2022). "In this study, we used STZ to induce T2D in the HFD-fed ApoE-/- mice in order to investigate the progression of atherosclerosis in T2D mice." (PMID 36286043, 2022). "Here, our in vivo data showed that therapeutic sclerostin antibody elevated serum levels of inflammatory cytokines and chemokines, and aggravated AA and atherosclerosis in Col1a2+/G610C.ApoE-/- mice with AngII infusion." (PMID 35966595, 2022). "During the course of our study, a report described that VX765 impeded atherosclerosis in ApoE−/− mice." (PMID 35641492, 2022). "The present study demonstrated the novel role of homoplantaginin and dihydrohomoplantagin in protection against oxLDL-induced injury in endothelial cell and the development of atherosclerosis in apoE-/- mice." (PMID 35335352, 2022). "The function of MSR1 in the pathogenesis of atherosclerosis appears to be dependent on the mouse genetic background and apoE presence." (PMID 36325338, 2022). "Here, the targeted inhibition of miR-29 using a locked-nucleic acid strategy in a murine model of atherosclerosis (ApoE−/− mice) promoted a significant reduction in atherosclerotic lesion size and further enhanced fibrous cap thickness and plaque stability." (PMID 35758143, 2022). "In mouse models of atherosclerosis, such as LDL receptor deficiency or ApoE deficiency, genetic ablation of RIPK3 reduces both advanced atherosclerotic lesions and lesional inflammation." (PMID 39872161, 2022). "Accelerated atherosclerosis in SR-B1/ApoE dKO mice, partly due to abnormal lipoproteins, leads to coronary artery occlusion, MI, and premature death 5 ~ 8 weeks after birth." (PMID 35332444, 2022).